SMOC1 (SPARC related modular calcium binding 1)
Diseases named in the same sentence as SMOC1 in open-access papers (continued):
Sharing a sentence is not in itself a finding about the gene and the disease.
cancer (18 papers, 2018 to 2025). A tumor composed of atypical neoplastic, often pleomorphic cells that invade other tissues. "SMOC1 is a cancer-associated protein, identified as an extracellular glycoprotein of the SPARC-related modular calcium-binding protein family." (PMID 33828913, 2021). "Finally, we investigated DNA methylation of cancer-associated genes including SMOC1 as well as CIMP marker genes in TSAs because it was reported that SMOC1 is specifically methylated in TSAs." (PMID 32092099, 2020). "SMOC1 is a calcium-dependent conformational glycoprotein and a true basement membrane component, which has been suggested to be a new cancer-related protein and has been shown to interact with TNC in vitro." (PMID 36292695, 2022). "In this study, we aimed to systematically explore the gene expression and evaluate the prognostic values of SMOC1 in different cancers and uncover the potential functions of SMOC1 in specific cancers." (PMID 34869577, 2021). "To further explore the expression of SMOC1 in pan-cancers, we analyzed the RNA-seq data from TCGA using the TIMER database." (PMID 34869577, 2021). "The expression levels of SMOC1 were higher in the kidney, brain, and central nervous system (CNS) cancers compared with the corresponding normal tissues." (PMID 34869577, 2021). "Then, we further evaluated the relationships between SMOC1 expression and prognosis in 33 cancer types from the TCGA project in GEPIA2." (PMID 34869577, 2021). "To evaluate the prognostic value of SMOC1 in different types of cancers, we analyzed the correlations between SMOC1 expression and survival of human cancers in different databases." (PMID 34869577, 2021). "By contrast, the vast majority of SSA/Ps with cancer exhibited BRAF mutation and CIMP-high, while SMOC1 methylation was infrequent in both the SSA/P and cancer tissues." (PMID 29435136, 2018). "In contrast to the other family members, few studies have shown possible involvement of SMOC1 in cancer." (PMID 29435136, 2018). "We therefore generated a receiver operating characteristic (ROC) curve to assess the ability of SMOC1 methylation levels to distinguish pure TSAs from TSAs with cancer and found the most discriminating cutoff value to be 36% (sensitivity, 75%; specificity, 66%)." (PMID 29435136, 2018). "Finally, we examined the effect of SMOC1 depletion in cancer cells." (PMID 29435136, 2018). "We found that levels of SMOC1 methylation were higher in TSAs associated with cancer than in those without cancer, suggesting SMOC1 methylation may be a marker identifying TSAs at high risk of developing CRC (data not shown)." (PMID 29435136, 2018). "Moreover, SMOC1 was identified as a new cancer-related protein by interacting with tenascin-c, which was an ECM protein and was highly expressed in many human cancers." (PMID 34869577, 2021). "Due to the lack of adjacent normal tissue, the changes of SMOC1 expression in cancers such as LGG and GBM were unable to show." (PMID 34869577, 2021). "Similarly, testis-restricted targets such as SPA17, TEX14, LAMA1, SMOC1, TNFAIP6, GPC2, and COL20A1 may also be leveraged for their cancer-specificity." (PMID 38702309, 2024).
infection (7 papers, 2009 to 2022). The state of being infected such as from the introduction of a foreign agent such as serum, vaccine, antigenic substance or organism. "Indeed, Bmp2 and Runx2 synergistically induced Smoc1 and Smoc2 expressions as an early response to infection." (PMID 34667264, 2021).
neurodegenerative disease (2 papers, 2024). A disorder of the central nervous system characterized by gradual and progressive loss of neural tissue and neurologic function. "SMOC1 is significantly increased in the CSF of AD patients when compared to cognitively normal controls or other neurodegenerative diseases." (PMID 39574902, 2024).
cardiovascular diseases (1 paper, 2021). "However, the role of miR-211-5p and SMOC1 in cardiovascular diseases has rarely been studied." (PMID 34631806, 2021).
SMOC1 also shares sentences with these, for which no sentence is quoted: COVID-19 (8 papers); viral infections (8); Anophthalmia (3); autoimmune disease (3); cognitive decline (3); astrocytic tumor (2); Flavivirus Infections (2); HIV-1 infection (2); Lewy body dementia (2); lung carcinoma (2); ovarian carcinoma (2); pancreatic neuroendocrine tumor (2); prostate carcinoma (2); psoriasis (2); bladder urothelial carcinoma (1); cartilage disease (1); cholangiocarcinoma (1); chronic myelogenous leukemia (1); coronary artery calcification (1); dengue (1); dermatomyositis (1); diverticulosis (1); encephalitis (1); fatty liver disease (1); head and neck cancer (1); heart failure (1); Hypercholesterolemia (1); hyperplastic polyp (1); infectious disease (1); Infertility (1).
A further 22 diseases each share a sentence with SMOC1 in 1 paper.